HLA-B (major histocompatibility complex, class I, B)
Diseases named in the same sentence as HLA-B in open-access papers (continued):
Sharing a sentence is not in itself a finding about the gene and the disease.
ankylosing spondylitis (continued). "Originally, the HLA‐B*27:05 genotype was associated with ankylosing spondylitis and other systemic inflammatory diseases, such as psoriasis, inflammatory bowel disease, and reactive arthritis." (PMID 33031633, 2020). "For HLA-B*27:05, an allele with high association to several diseases, including ankylosing spondylitis, we recorded allele frequency between 4.8 and 8.0%." (PMID 31844174, 2020). "Some of the most striking odds of disease are seen with autoimmune conditions such as the association between ankylosing spondylitis and possession of HLA-B*27 (odds ratio >100) or between Behçet’s Disease and HLA-B*51 (accounts for 32–50% of cases)." (PMID 32238263, 2020). "Stepwise conditional logistic regression analysis of HLA-B allelic associations with ankylosing spondylitis in the Turkish and Iranian cohorts." (PMID 30946743, 2019). "HLA-B*27 predisposes for ankylosing spondylitis, inflammatory bowel disease, and psoriasis arthritis, creating an overlapping HLA-class I risk pattern although no autoantigens have been identified in these diseases." (PMID 29760713, 2018). "The most prominent of these associations concern birdshot chorioretinopathy (BSCR), ankylosing spondylitis (AS), Behçet's disease (BD) and psoriasis, which involve HLA-A*29:02, HLA-B*27, HLA-B*51, and HLA-C*06:02, respectively." (PMID 30425713, 2018). "It was therefore necessary to formalize the diagnostic criteria of ankylosing spondylitis, using “objective evidence,” like HLA-B*27, to control the therapeutic requirements." (PMID 26528326, 2015). "The presence of the HLA-B*27 allele is a major risk factor for the development of ankylosing spondylitis (AS), which causes chronic inflammation of the spine and other sites." (PMID 26613595, 2015). "Ankylosing spondylitis (AS) is a common, highly heritable, inflammatory arthritis for which HLA-B*27 is the major genetic risk factor, although its role in the aetiology of AS remains elusive." (PMID 25994336, 2015). "The previously reported MHC Class I region including HLA-C and HLA-B (associated with psoriasis and ankylosing spondylitis, respectively) was associated only in the EA dataset." (PMID 22952805, 2012). "HLA-B*1403 is the predominant allele in patients affected by ankylosing spondylitis from West Africa, where HLA-B*27 is uncommon." (PMID 17480220, 2007). "There exists more clear evidence regarding the risk conferred by HLA-ABC alleles to other autoimmune diseases, with associations reported for HLA-B*27 and ankylosing spondylitis, HLA-C*06:02 and psoriasis, HLA-B*51 and Behçet’s disease, and HLA-A*29 with birdshot chorioretinopathy." (PMID 41444678, 2025). "Likewise, a statistically significant association has been reported between several autoimmune conditions and specific HLA alleles, for example, HLA-B*27 and ankylosing spondylitis." (PMID 39812071, 2025). "The HLA-B*27 allele subtypes are associated with ankylosing spondylitis." (PMID 39201523, 2024). "Notably, this cysteine is also a key feature of the pathogenic ankylosing spondylitis associated allele HLA-B*27." (PMID 39468056, 2024). "The most relevant example is the association between HLA-B*27 and ankylosing spondylitis." (PMID 38535155, 2024). "In contrast, HLA class I associations with autoimmune conditions are less common, however, they still have a strong association with conferring disease risk such as in the case of HLA-B*27 which the strongest genetic contributors to ankylosing spondylitis in Europeans." (PMID 39355248, 2024). "Therefore, the lack of active ERAP2 enzyme in allotype B homozygotes results in changes in the immunopeptidome, as it was shown for HLA-B*27, associated with ankylosing spondylitis." (PMID 35769458, 2022).
ankylosing spondylitis (continued). "For example, in Ankylosing Spondylitis, variant G in rs30187 (R528) appears to be protective in subjects positive for HLA-B*27, the major susceptibility gene in AS, whereas it is a risk factor for Behçet’s disease in carriers of HLA-B*51, the allele more strongly associated with BD." (PMID 36203608, 2022). "Of interest, evasion of Tregs-mediated suppression may explain the association of autoimmunity with HLA-B*27 and HLA-B*57 alleles (e.g. ankylosing spondylitis and psoriasis)." (PMID 32760139, 2020). "The association with HLA-C*06:02 in psoriasis is particularly intriguing because only 3 of more than 12,000 different HLA-class I alleles show a strong disease linkage: HLA-B*27 with ankylosing spondylitis, HLA-B*51 with Behçet’s disease, and HLA-C*06:02 with psoriasis." (PMID 29760713, 2018). "This single difference at P156, essential in D and E peptide-binding pockets, may play a role in the differential association of HLA-B*14:02 and HLA-B*14:03 with ankylosing spondylitis." (PMID 28878089, 2017). "The strongest association identified concerns the HLA-B*27 allele and the ankylosing spondylitis." (PMID 26528326, 2015). "Ankylosing spondylitis was notably more frequent among HLA-B*27-positive patients (22.73% vs. 3.57%; p = 0.039), consistent with established immunogenetic patterns." (PMID 40868248, 2025). "(2019) set out to identify differentially methylated CpG sites in HLA-B*27-positive individuals with ankylosing spondylitis." (PMID 39355248, 2024). "It was shown that peptide processing and presentation by HLA-B molecules play a crucial role in the development of Ankylosing Spondylitis." (PMID 38892265, 2024). "Another important example of the significance of the genotyping method is HLA-B*27 test commonly used to genetically confirm a diagnosis of ankylosing spondylitis." (PMID 35566618, 2022). "We found a moderate level of evidence for the presence of concomitant PsA in Pso for HLA-B*27, known for its high prevalence (90%) in ankylosing spondylitis (AS)." (PMID 34127053, 2021). "Ankylosing spondylitis and reactive arthritis were more common in the HLA-B patients group, but the difference with the HLA-B27− group does not meet criteria to be statistically significant (p > 0.05)." (PMID 33014440, 2020). "Furthermore, documented correlations exist between HLA-B*13, HLA-B*47, and HLA-B*51 and the pathogenesis of ankylosing spondylitis." (PMID 40428751, 2025). "Ankylosing spondylitis was significantly more common in HLA-B*27-positive patients (22.73%) than in those who were negative (3.57%), with a statistically significant association confirmed by a chi-square test (χ2 = 4.281, p = 0.039) and a weak but meaningful phi coefficient (φ = 0.293)." (PMID 40868248, 2025). "The authors mentioned a correlation between ankylosing spondylitis (AS) and HLA-B*27." (PMID 41614782, 2025). "In addition to HLA-B*27, several other major histocompatibility complex (MHC) class I molecules have been implicated in the susceptibility to ankylosing spondylitis." (PMID 40428751, 2025). "Some HLA-B27 alleles are now known to have a stronger association with the development of ankylosing spondylitis (AS), such as HLA-B*27:05, whereas HLA-B*27:06 and HLA-B*27:09 would not be related to AS risk." (PMID 38746054, 2024). "The human leukocyte antigen (HLA)-B*27 carriage is strongly related to the development of spondyloarthritis (SpA), a group of chronic inflammatory rheumatic diseases, whose prototype is ankylosing spondylitis (AS)." (PMID 37686141, 2023). "We also found multiple associations in rare alleles (MAF < 1%), including the novel HLA-B*57:31:02 in psoriasis (OR = 4.61, 95% CI: 3.22–6.59, p = 7.1 × 10−17, EAF = 0.06%) and HLA-C*02:178 in ankylosing spondylitis (OR = 5.33, 95% CI: 3.37–8.41, p = 7.75 × 10−13, EAF = 0.2%)." (PMID 37923823, 2023).
ankylosing spondylitis (continued). "HLA-B*27 is associated with a more chronic and extensive disease course in male children and adolescents with enthesitis-related arthritis (ERA) and with a better response to anti-TNF treatment in ankylosing spondylitis." (PMID 37277844, 2023). "Whereas the subtypes HLA-B*27:05, -:04, and -:02 are associated with ankylosing spondylitis, HLA-B*27:06 and HLA-B*27:09 are not, despite HLA-B*27:05 and 27:09 differing by one amino acid." (PMID 35254093, 2022). "For instance, HLA-B*27:05 has been found to cause ankylosing spondylitis, while HLA-B*27:09 does not have an effect in the disease predisposition." (PMID 33528690, 2021). "Allele and genotype frequency distribution for IL10 −1082 A>G and the association with the risk for ankylosing spondylitis, regardless of HLA-B*27 marker and age in different genetic models." (PMID 34290697, 2021). "Moreover, an annoying consequence of misunderstanding sometimes occurs when rheumatologists have to deny a diagnosis of ankylosing spondylitis, while the patient is positive for HLA-B*27." (PMID 26528326, 2015). "Therefore, in this study, we chose to document the use of one marker of a multifactorial disease: HLA-B*27, because it has several unique features and a long history of clinical use in relation with ankylosing spondylitis." (PMID 26528326, 2015). "The single amino acid replacement Asp116His distinguishes the two subtypes HLA-B*2705 and HLA-B*2709 which are, respectively, associated and non-associated with Ankylosing Spondylitis, an autoimmune chronic inflammatory disease." (PMID 22403718, 2012). "Moreover, though PLD6 was not detectable in RA, it is reported that carrying HLA-B*27 was associated with robust hypomethylation of PLD6 in ankylosing spondylitis patients." (PMID 37325646, 2023). "While a small odds ratio and a high false-discovery rate (P value adjusted for testing 81 HLA types = 0.68), this finding was of particular interest as HLA-B*27 has been associated with nontyphoidal Salmonella-induced reactive arthritis and ankylosing spondylitis (15, –, 18)." (PMID 35254093, 2022). "Accordingly, the main risk factors for Ankylosing Spondylitis (AS), prototype of the Spondyloarthropathies (SpA), the Behçet’s disease (BD), the Psoriasis (Ps) and the Birdshot Chorioretinopathy (BSCR) are HLA-B*27, HLA-B*51, HLA-C*06:02 and HLA-A*29:02, respectively." (PMID 33348540, 2020). "Ankylosing Spondylitis (AS), Psoriasis (Ps), Birdshot Chorioretinopathy (BSCR) and Behçet’s disease (BD) are referred as “MHC-I-opathies” as they share an association with HLA-class I genes, in particular HLA-B*27, HLA-C*06:02, HLA-A*29:02 and HLA-B*51, respectively." (PMID 33348540, 2020). "First, regarding the individual issues that may occur, including psychological issues, it seems indeed that they are not directly linked to HLA-B*27 test, but rather to the diagnosis of ankylosing spondylitis." (PMID 26528326, 2015). "Similarly, the absence of HLA-B*27:05 in Africa is supported by the uncommon presentation of ankylosing spondylitis (AS) disease." (PMID 40603473, 2025). "Similarly, the absence of HLA-B*27:05 in African is supported by the uncommon presentation of ankylosing spondylitis (AS) disease." (PMID 39282263, 2024).
psoriasis (70 papers, 2008 to 2026). An autoimmune condition characterized by red, well-delineated plaques with silvery scales that are usually on the extensor surfaces and scalp. "HLA-B*38:01 has been linked to an increased risk of developing psoriatic arthritis (PsA) among individuals with psoriasis." (PMID 41512531, 2026). "In a previous study conducted in a Pakistani population, the HLA-B*15:01 allele was associated with late-onset psoriasis." (PMID 41512531, 2026). "Less frequently associated HLA-class I-alleles which also confer susceptibility to psoriasis are HLA-C*07:01, HLA-C*07:02, HLA-C*12:02, HLA-C*07:04, HLA-B*27, and HLA-B*57." (PMID 40243413, 2025). "Genomic biomarkers include HLA alleles: HLA-B*27, -B*38, -B*39, and -B*8 have been identified as specific markers for PsA among psoriasis patients." (PMID 40284188, 2025). "Other HLA class I alleles associated with a risk of psoriasis are HLA-C*07:01, HLA-C*07:02, HLA-C*07:04, and HLA-B*27:05, with HLA-B*27:05 and HLA-C*06:02 being phenotype-defining risk alleles also for psoriatic arthritis." (PMID 41440022, 2025). "Within the cohort, both HLA-B*13 and HLA-B*57 alleles were associated with psoriasis, while HLA-B*37 and HLA-B*41 alleles were clustered within the reactive arthritis group." (PMID 40806743, 2025). "SNP rs13437088, situated at the 16 kb telomeric region of MICA and 30 kb centromeric region of HLA-B, exhibited a robust association with Han Chinese psoriasis after adjusting the effect of the imputed HLA-Cw*0602." (PMID 38474281, 2024). "Whereas the correlation of HLA-C*06:02 with psoriasis is more pronounced than with psoriatic arthritis, other HLA variants such as HLA-B*27, HLA-B*39, HLA-B*38, and HLA-B*08 have been related with the development of psoriatic arthritis." (PMID 37628670, 2023). "The presence of the HLA-B*27 allele, psoriasis, IBD, or recent infection in these patients facilitates the diagnosis of this disease." (PMID 34199710, 2021). "The presence of the HLA-B*35 allele in un-axSpA patients can also raise awareness of the possible development of psoriasis and IBD and help in the choice of therapeutic modalities." (PMID 34199710, 2021). "The locus demonstrating the strongest effect on risk is the MHC region, with several alleles of HLA-C and HLA-B conferring a 2-4-fold increased risk of psoriasis." (PMID 34177931, 2021). "When we conditioned on HLA-C and NOTCH4, we observed an independent association at HLA-B amino acid position 67 (B-Y67C, OR = 1.80, P = 5.45 × 10−11), which was previously reported to be associated with psoriasis in both European and Han Chinese populations." (PMID 33134369, 2020). "Noteworthy, HLA-B*27, which is among the HLA class I alleles predisposing to Psoriasis, presents an immunopeptidome partly overlapping with that of HLA-C*06:02 characterized by shared anchor residues at P2 and P9." (PMID 33348540, 2020). "The presence of HLA-B*27:05 and HLA-B*39:01 is associated with less time lag between psoriasis and PsA [18–20••]." (PMID 32166449, 2020). "HLA-B*27 was associated with early development of PsA among patients with psoriasis, whereas the presence of HLA-C*06 was associated with a delayed onset of PsA29." (PMID 31583079, 2019). "The same HCP5 and HLA-B genotypes were associated with psoriasis (PS) and psoriatic arthritis (PSA) and found to be a major determinant of flucloxacillin-induced liver injury." (PMID 31137555, 2019). "Helms observed in the study that, although HLA-C∗06:02 was found in the majority of overtransmitted haplotype harboured by HLA-C∗12:03, HLA-C∗12 was also associated with HLA-B alleles that play a role in psoriasis (HLA-B∗38:01 and HLA-B∗901)." (PMID 31341424, 2019). "HLA-C∗12 alleles are also associated with HLA-B group alleles that are related to psoriasis (HLA-B∗38:01 and HLA-B∗39:01) in Caucasians." (PMID 31341424, 2019). "The associations of HLA-B*51 and C*06:02 with BD and psoriasis are lower, yet quite significant, with odds ratios around 5–6." (PMID 30425713, 2018).
psoriasis (continued). "Most of these novel potential psoriasis-associated SNPs are reported to be Expression quantitative trait loci (eQTLs) of known psoriasis-associated genes like HLA-B and HLA-C in GTEx Portal29." (PMID 30315195, 2018). "Genetic association studies have identified HLA-B*08, HLA-B*27, HLA-B*38 and HLA-B*39 as strong risk factors for PsA development in psoriasis patients." (PMID 29364831, 2018). "Aside from HLA-C*06:02 psoriasis associated with HLA-C*12:03, HLA-C*07:01, HLA-C*07:02, HLA-C*07:04, HLA-B*27, and HLA-B*57." (PMID 29760713, 2018). "When testing for association of HLA variants with PsA risk versus psoriasis risk, the strongest association was found with HLA-B amino acid position 45, for which HLA–B Glu45 was found to increase PsA risk compared with psoriasis risk." (PMID 26255310, 2016). "As a result, it was reported that risk heterogeneity between PsA and psoriasis is driven by variants of HLA-B." (PMID 26255310, 2016). "We also found that the compound genotype KIR3DS1 plus HLA-B Bw4-80I, which respectively encode a natural killer cell activating receptor and its putative ligand, significantly increased psoriasis susceptibility." (PMID 22577363, 2012). "Our HLA data revealed that psoriasis is associated with HLA-B alleles carrying the Bw4 epitope (p = 1.28×10−25, OR = 1.66)." (PMID 22577363, 2012). "SNP rs9468925 in HLA-C/HLA-B consistently appears in all four regression models, indicating that an independent HLA locus is associated with psoriasis." (PMID 22125590, 2011). "Although MICA is strongly in LD with HLA-B, it has been associated with psoriasis and evidenced for an association independently of HLA-B/C with psoriatic arthritis in Jewish population." (PMID 22125590, 2011). "Minor allele at rs9468925 in HLA-C/HLA-B appear to be negatively associated with psoriasis in all four models (OR = 0.53–0.65, P = 1.22e-08 to 1.70e-05)." (PMID 22125590, 2011). "More importantly, although the linkage disequilibrium patterns and the HLA-B tagging SNPs were different between Chinese and white populations, the same HLA-B serotypes were associated with psoriasis: B*57 with an increased risk and B*40 with a reduced risk." (PMID 19680446, 2009). "Although most findings did not meet the p < 0.05 threshold in Fisher’s test, notable associations included HLA-B*15 with reduced lumbar mobility (p = 0.033), B*37 with dactylitis (p = 0.017), B*50 with arthritis (p = 0.012), and B*57 with psoriasis (p = 0.017)." (PMID 40806743, 2025). "Additionally, the rs4349859 SNP in the HLA-B gene, specifically associated with HLA-B27, was implicated in an increased risk of psoriasis and psoriatic arthritis." (PMID 37569685, 2023). "However, certain genes seem to be more frequently associated with PsA than psoriasis alone (i.e. the PsA-weighted genes such as HLA-B, FBXL19, and NOS2)." (PMID 33581710, 2021). "HLA-B allotypes also bind to regulatory leukocyte immunoglobulin-like receptors (LILRs) on antigen presenting cells with differential affinity, which we have also shown associates with psoriasis susceptibility." (PMID 34177931, 2021). "Both psoriasis and psoriatic arthritis also have associations with HLA-B alleles." (PMID 32888428, 2020). "The crucial role of the antigen presentation in the onset of disease is also indicated by the observation that at least three HLA-class I-associated diseases, AS, Behçet, and psoriasis (Ps), associated with HLA-B*27, HLA-B*51, and HLA-C*06, respectively, share an association with ERAP1." (PMID 29163539, 2017). "When analysing PsA risk and psoriasis risk separately, the strongest association observed among the HLA variants was with HLA-C*0602, which when conditioned upon revealed an independent contribution from HLA-B." (PMID 26255310, 2016).